SPHK2 (sphingosine kinase 2)
Diseases named in the same sentence as SPHK2 in open-access papers (continued):
Sharing a sentence is not in itself a finding about the gene and the disease.
cancer (continued). "It has been reported that main enzyme that produces S1P is SPHK1, not SPHK2 in cancer cells." (PMID 30018456, 2018). "Genes such as NRAS, SPHK2, FOS, CXCR4, PLD1, GNAI2, and PLA2G4F, and their related biological process terms and pathways, such as apoptosis, MAPK signalling pathway, and cancer signalling pathways, may represent potential targets for OA treatment and diagnosis." (PMID 29968759, 2018). "In contrast, the role of Sphk2 in cancer has not been well characterized." (PMID 26956050, 2016). "FTY720 analogues that are not targets for phosphorylation by sphingosine kinase-2, such as AAL(S), may have fewer toxicities and be more useful anti-cancer drugs." (PMID 27329844, 2016). "Therefore, SPHK1 and SPHK2, as well as S1P itself, have been recognized as promising targets for cancer treatment, and many SPHK inhibitors, either selective or non-selective for SPHK1 and SPHK2, have been developed, some of which are now being used in clinical trials." (PMID 29208982, 2017).
tumor (83 papers, 2013 to 2025). "Recently, many findings illustrated that overexpression of sphingosine kinase 2 (SphK2) is associated with drug resistance in tumor cells." (PMID 36891274, 2023). "TAMs from SphK2-deficient tumors displayed a pronounced anti-tumor phenotype, showing an increased expression of the pro-inflammatory markers/mediators such as NO, TNF-α, IL-12 and MHCII and a low expression of anti-inflammatory IL-10 and CD206." (PMID 35756630, 2022). "We further showed that downregulation of CERT was responsible for the tumor-suppressive effects of SphK2 deficiency." (PMID 36333295, 2022). "The phase I clinical trial of ABC294640 (NCT01488513) in patients with cholangiocarcinoma has been completed, demonstrates the pharmacological inhibition of SphK2 subsequently causes caspase-dependent apoptosis and attenuation of tumor growth." (PMID 33920887, 2021). "In further studies, SPHK2 inhibitor needs to be used to prove that S1P is responsible for the promotion of tumor growth and cell mitochondrial respiration caused by ACER2 overexpression." (PMID 33093451, 2020). "Alternatively, an S1P-dependent macrophage polarization toward the M1 phenotype in an Sphk2-deficient tumor xenograft model has been reported." (PMID 29518138, 2018). "We have previously shown that the sphingosine kinase 2 selective inhibitor ABC294640 has broad anti-tumor activity, that its effects mimic SphK2 ablation, and that loss of SphK2 impacts tumor growth more profoundly than loss of SphK1." (PMID 27517489, 2016). "In accordance, a large increase of SK1 protein is associated with an increased infiltration of macrophages into tumor tissues of Sphk2−/− mice developing colitis-associated cancer." (PMID 27708249, 2016). "S1P produced by SPHK2 in breast tumour cells was reported to induce a pro-tumourigenic, anti-inflammatory phenotype (referred to as the M2 phenotype) in tumour-associated macrophages." (PMID 24970218, 2014). "Data suggested that tumor-associated macrophages (TAMs) in the SphK2-deficient tumors displayed a pronounced antitumor phenotype, with an increased expression of proinflammatory markers/mediators such as NO, TNFα, IL-12, and MHCII and a low expression of anti-inflammatory IL-10 and CD206." (PMID 29269995, 2017). "Future studies should prioritize developing mass spectrometry-based assays to measure SphK2-derived S1P in tumor biopsies or non-invasive liquid biopsies." (PMID 41446733, 2025). "Our single-cell sequencing analyses further elucidated the relationship between microbial SphK2 activity and dynamics of tumor-infiltrating T cell lineages." (PMID 41446733, 2025). "The overexpression of SPHK2 has a tumor-promoting effect; that is, it can promote the proliferation, migration and invasion of tumor cells." (PMID 38965120, 2024). "We and others have demonstrated that inhibition of sphingosine kinase-2 by the small-molecule investigational drug opaganib (formerly ABC294640) kills tumor cells and increases their sensitivities to other drugs and radiation." (PMID 38069222, 2023). "In contrast, tumour-promoting inflammation in the sigmoid colon of UC depended on the overexpression of SPHK2." (PMID 37298127, 2023). "Knockout of Sphk2 suppressed HFHSD-induced HCC in mice, associated with inhibition of hepatic cell proliferation in a tumor-suppressive microenvironment." (PMID 36333295, 2022). "The anti-tumor effect of Sphk2 siRNA was also demonstrated in a xenograft mouse model resulting in reduced HCC tumor progression." (PMID 35912267, 2022). "SphK, with two isoforms (SphK1 and SphK2), is a bioactive enzyme capable of converting sphingosine into S1P, which is a lipid mediator playing a major regulatory role in tumor cell growth, survival, invasion, angiogenesis and therapeutic resistance." (PMID 35184376, 2022). "Initially, SphK2 was considered to be a proapoptotic protein because overexpression of SphK2 promoted tumor apoptosis." (PMID 35178477, 2022).
tumor (continued). "The mRNA and protein expression of SphK1 and SphK2 in pCCa-1 tumor tissues were unchanged after SKI-V treatment." (PMID 35541904, 2022). "This fits to observations in breast cancer xenografts where ablation of SPHK2 in tumor cells reduced pro-tumor features of infiltrating macrophages." (PMID 35163211, 2022). "Although early studies proposed a possible proapoptotic/anticancer function of SphK2, accumulating evidence suggests that SphK2/S1P has tumor-promoting activity similar to SphK1/S1P." (PMID 33968977, 2021). "In the current study, we found that both phospho-SphK1 and phospho-SphK2 were significantly correlated with the FSHR level in tumour tissue." (PMID 32796926, 2020). "Previous studies demonstrate that miR-577 is a well-recognized tumor suppressor and it negatively regulates a lot of oncogenes and oncogenic pathways, including Sphk2, Smurf1, Rab14, Rab25, LRP6, β-catenin, Wnt2b, and so on." (PMID 33069244, 2020). "Knockdown or pharmacological inhibition of SphK2 can decrease tumor proliferation and metastasis and increase apoptosis in vivo and in vitro." (PMID 32670862, 2020). "While Sphk1 has historically been more intensely studied due to its prominent role in tumor cell proliferation, recent investigations have increasingly focused on understanding potentially unique functions of Sphk2." (PMID 29518138, 2018). "Conversely, other contributions have shown that, in human colon carcinoma cells, S1P generated by nuclear SphK2 can inhibit the retinoic acid receptor β, attenuating the tumor suppressor effects of this receptor." (PMID 28878674, 2017). "Inhibition of SPHK2 attenuated tumor growth by induction of caspase 3-mediated cell apoptosis via enhancing the degradation of anti-apoptotic protein Mcl-1, and increasing the expression of a pro-apoptotic protein Noxa." (PMID 29145490, 2017). "When analyzing tumor tissue lysates, we showed that SphK2 expression was indeed downregulated in tumors expressing SphK2-shRNA or miR-19a-3p (two sets)." (PMID 29285269, 2017). "Studies indicate that sphingosine kinase 2 (SphK2) promotes tumor progression in NSCLC, but how this occurs is unclear." (PMID 28428733, 2017). "As a whole, these data contribute to our understanding of the roles of SphK2 in tumor biology, further supporting critical roles for sphingolipids as regulators of gene expression." (PMID 27517489, 2016). "These often conflicting studies indicate that the roles played by SPHK2 in cell proliferation and the tumour microenvironment are highly dependent on cell type and physiological context." (PMID 24970218, 2014). "Activation of canonical NF-κB activation during KSHV infection promotes viral latency and survival for KSHV-infected cells, and previously published data indicate that inhibition of SphK2 suppresses NF-κB activation in tumor cell lines." (PMID 25010828, 2014). "After combination therapy, the SphK2-high activity group manifested significantly elevated T cell infiltration when compared to the SphK2-low group, suggesting enhanced T cell-mediated anti-tumor immunity in the former group." (PMID 41446733, 2025). "The results of this study showed that Lathyrol may affect the invasion and EMT activity of RCC xenografts by affecting the secretion of SPHK-2.MMPs and uPA promote tumor infiltration and invasion in the TME." (PMID 38965120, 2024). "S1P, a bioactive sphingolipid metabolite being produced by one of two sphingosine kinase isoforms (SPHK1 or SPHK2), can be released through transporters into the tumor microenvironment to influence tumor cells as well as immune cells, contributing to carcinogenesis." (PMID 36600310, 2023). "Thus, SphK2 generated S1P enhances the supportive character of the tumor microenvironment by modulation of macrophage polarization towards the M2 phenotype." (PMID 35756630, 2022). "However, it was subsequently found to be a prosurvival factor, as inhibition of SphK2 suppressed the tumor growth." (PMID 35178477, 2022).
tumor (continued). "The results from the present study and others suggest that SphK2 is involved in tumor metastasis and that SphK2 might be a therapeutic target in TNBC." (PMID 33968977, 2021). "Moreover, inhibition of SphK2 using ABC294640 was reported to induce autophagy-mediated cell death and tumor suppression in Kaposi sarcoma-associated herpes virus-related tumors." (PMID 34069611, 2021). "The genetic ablation of SphK2 suppressed the tumor growth in breast tumor xenografts (MCF-7)." (PMID 33920887, 2021). "In addition, it was reported that SphK2 regulated tumor malignancy via modulating the AKT/β-catenin pathway." (PMID 34305532, 2021). "Interestingly, the differentiated HSkM+ cells displayed a significantly increased SPHK1 and SPHK2 protein content compared to the undifferentiated HSkM− control and the tumor cell lines." (PMID 31455837, 2020). "Accumulating evidence has revealed that SphK2 is overexpressed in tumor tissues and cell lines." (PMID 32670862, 2020). "The volumes of tumor expressing SphK2-shRNA or miR-19a-3p were much lower than the control tumors." (PMID 29285269, 2017). "S1P generated by nuclear SphK2 binds to hTERT allosterically mimic phosphorylation and maintains telomere integrity and stability through limiting proteasome degradation and enhances tumor growth." (PMID 29269995, 2017). "SphK2 mRNA in tumor tissues was about 4-5 times higher than the normal tissues." (PMID 29285269, 2017). "However, the biological functions of Sphk2 are largely different from Sphk1: Sphk1 acts as an oncogene and Sphk2 exerts tumor suppressive roles in colorectal carcinogenesis and progression." (PMID 28991193, 2017). "To investigate the role of HULC in tumor angiogenesis, we screened the expression of several tumor angiogenesis-associated factors, such as VEGF, SPHK2, transforming growth factor-beta receptor 2 (TGF-βR2), monocyte chemoattractant protein 1 (MCP1) and SPHK1, in HULC over-expressed HepG2 cells." (PMID 26540633, 2016). "Furthermore, inhibition of the NF-κB cascade with a sphingosine kinase-2 inhibitor decreased NF-κB activation as well as tumor growth in vitro and in vivo." (PMID 25926105, 2015). "It has been reported that over-expression of SPHK2 decreases cell growth and enhances apoptosis, which seems to suggest that it may function as a tumor suppressor." (PMID 25153718, 2014). "While the importance of SphK2 in HNSCC is unknown, SphK1 has been implicated in tumor growth and cell transformation in HNSCC." (PMID 24970177, 2013). "Thus, low expression of SphK2 in oral squamous cells may suppress apoptosis, thereby contributing to neoplasia." (PMID 35494957, 2022). "Additionally, SPHK2-generated nuclear S1P was observed to bind directly to human telomerase reverse-transcriptase (hTERT), preventing hTERT from ubiquitination and proteasomal degradation (stabilizing telomerase), leading to enhanced tumor growth." (PMID 35565311, 2022). "The two isoforms of SphK, SphK1, and SphK2, catalyse the conversion of the membrane phospholipid sphingosine to the bioactive lipid S1P, an oncogenic mediator which drives a number of vital processes in tumor cells, including cell growth, survival, migration, invasion, and angiogenesis." (PMID 34768523, 2021). "Alternatively, nuclear SPHK2-derived S1P has been shown to bind hTERT and allosterically mimic protein phosphorylation which limits proteasomal degradation and maintains telomere integrity and stabilization, thereby, bypassing replicative senescence and enhancing tumor growth." (PMID 31891125, 2018). "Specifically, when HeLa cells are stimulated by the tumor promoter phorbol 12-myristate 13-acetate (PMA), a novel putative nuclear export signal (NES) motif within SPHK2 is specifically phosphorylated." (PMID 41234914, 2025). "In targeted therapy, SphK1 inhibitors (e.g., PF-543) and SphK2 inhibitors (e.g., ABC294640) have shown significant anti-tumor effects in preclinical models." (PMID 41234914, 2025).
tumor (continued). "Among CRC patients with high microbial SphK2 activity, combination therapy induced a significant expansion of effector memory CD8+ T cells within the tumor microenvironment, accompanied by a relative reduction in Tex cell subsets." (PMID 41446733, 2025). "SphK1 is highly expressed in HCC tissues, while SphK2, although less studied in HCC, can influence tumor cell behavior through regulation of gene expression and cell cycle progression." (PMID 41234914, 2025). "It was reported that METTL3 regulates HDGF in an m6A-mediated manner to promote tumor angiogenesis and glycolysis and also regulates ZMYM1, SPHK2, and MYC to promote GC tumor metastasis." (PMID 39195675, 2024). "Protein expression levels of SPHK2, metal matrix protease 2 (MMP2), MMP9 and urokinase-type plasminogen activator (uPA) in tumor tissues were assessed by immunohistochemistry (IHC)." (PMID 38965120, 2024). "In addition, it should be kept in mind that sphingosine-1-phosphate is a chemoattractant for T-cells, raising the question of whether SPHK2-generated sphingosine-1-phosphate in turn leads to a high infiltration of T-cells and ultimately to a pro-tumor, inflammatory environment?" (PMID 37106775, 2023). "Earlier, we reported that in approximately two-thirds of OSCC patients studied, mRNA expression of SphK2 and lipid phosphate phosphatase 3 (LPP3) was significantly downregulated in tumor tissues, compared with the same patient’s adjacent normal tissue." (PMID 35494957, 2022). "We have determined the protein expression of four S1P-metabolizing enzymes (SphK1, SphK2, sphingosine-1-phosphate phosphatase 1 (SGPP1), and lipid phosphate phosphatase 3 (LPP3)) by immunohistochemistry (IHC) in tumor tissues of 46 OSCC patients." (PMID 35494957, 2022). "After that, to further investigate the role of ubiquitination of SphK2 in vivo, a xenograft tumor-bearing model was established by inoculating NEDD4L overexpression plasmid and/or SphK2 overexpression plasmid transfected U251 into nude mice." (PMID 34305532, 2021). "In contrast, its ectopic upregulation suppresses tumor cell growth, migration, invasion, and EMT by targeting the 3′-UTR of SphK1 and SphK2 in the bladder and papillary thyroid cancers, respectively." (PMID 35201458, 2021). "This led to the further finding that SphK2/S1PR4 prevented nuclear translocation of S1PR2, which in turn, prevented tumor growth, providing support for sub-cellular distribution of S1PR2, which is important for oncogenic suppression." (PMID 28415564, 2017). "Fourth, SphK2 silence, by targeted-shRNA or miR-19a-3p, dramatically inhibited U2OS tumor growth in nude mice." (PMID 29285269, 2017). "Sphingosine is phosphorylated into a tumor promoter sphingosine-1-phosphate (Sph-1P), by sphingosine kinase 1 (SPHK1) or 2 (SPHK2)." (PMID 28445970, 2017). "Recently, we report that inhibition of sphingosine kinase 2 (SphK2) by a novel compound, ABC294640, effectively prevents and represses PEL tumor progression in vivo." (PMID 24708874, 2014). "We recently reported that pharmacologic inhibition of SphK2 using ABC294640 induces dose-dependent, caspase-mediated apoptosis for KSHV-infected PEL cell lines and suppresses PEL tumor progression in vivo." (PMID 25010828, 2014). "The SPHK2 inhibitor ABC294640, which also antagonises estrogen signalling, inhibits the growth of a number of different tumour cell lines in vivo, and has chemosensitizing properties." (PMID 24970218, 2014). "Use of specific SphK2 inhibitor ABC294640, [3-(4-chlorophenyl)-adamantane-1-carboxylic acid (pyridin-4-ylmethyl)amide], results in cell death and inhibition of tumor growth in kidney, prostate and breast tumor cell lines." (PMID 24970177, 2013). "Unlike SphK1, SphK2 remains understudied; nevertheless, it already appears to shape tumor fate by reprogramming transcriptional networks and cell-cycle checkpoints." (PMID 41234914, 2025).